LINC00598 (long independently transcribed non-coding RNA 598)
Synonyms: TTL; lncFOXO1; LINC00548
Gene: Long non-coding RNA gene on chromosome 13 (40,079,106 to 40,535,807, reverse strand). Ensembl gene ENSG00000215483.
Diseases named in the same sentence as LINC00598 in open-access papers:
LINC00598 is named in the same sentence as 3 diseases in open-access papers, as found by Europe PMC text mining. Sharing a sentence is not in itself a finding about the gene and the disease. The quoted sentences say what the papers report.
tumor (2 papers, 2019 to 2020). "Knockdown of LINC00598 was previously proved to induce G0/G1 cell cycle arrest and inhibit proliferation, indicating its tumor-promoting roles." (PMID 32149080, 2020).
LINC00598 also shares sentences with these, for which no sentence is quoted: breast carcinoma (1 paper); lung carcinoma (1).